NOD1 (nucleotide binding oligomerization domain containing 1)
Diseases named in the same sentence as NOD1 in open-access papers (continued):
Sharing a sentence is not in itself a finding about the gene and the disease.
dental caries (1 paper, 2016). The decay of a tooth, in which it becomes softened, discolored, and/or porous. "Regarding the progression of dental caries, our findings suggest that NOD1 expressed in odontoblasts detects peptidoglycan of gram-negative bacteria, such as iE-DAP, and induces the production of several chemokines as proinflammatory mediators of dental pulp inflammation." (PMID 27747243, 2016).
dental pulp inflammation (1 paper, 2016). "Therefore, our results suggest that NOD1 expressed in odontoblasts plays an important role in the progression of pulpitis because of the ability for chemokines upregulation." (PMID 27747243, 2016). "Our results strongly suggest that NOD1 expressed in odontoblasts transmits signals to the nucleus via the p38-AP-1 pathway and, therefore, may play important roles in the initiation and progression of pulpitis." (PMID 27747243, 2016).
diabetic cardiomyopathy (1 paper, 2024). Diabetic cardiomyopathy is a disorder of the heart muscle in people with diabetes. "In vitro data also support that high glucose induces diabetic cardiomyopathy by stimulating the NOD1/NF-κB pathway, promoting cardiac cell apoptosis, and enhancing myocardial fibrosis." (PMID 39906040, 2024). "NOD1 is capable of promoting the development of diabetic cardiomyopathy." (PMID 39906040, 2024).
diabetic retinopathy (1 paper, 2024). "Our study sheds light on the involvement of NOD1 in hematopoietic imbalance leading to local retinal inflammation and the progression of diabetic retinopathy." (PMID 38336763, 2024). "By regulating the infiltration of BMDMs, the production of chemoattractants, and subsequent neutrophil recruitment, NOD1 activation contributes to the NETosis-driven inflammation observed in diabetic retinopathy." (PMID 38336763, 2024). "However, further studies are warranted to comprehensively assess the safety profile and potential systemic effects of targeting NOD1 in bone marrow for the prevention and treatment of diabetic retinopathy." (PMID 38336763, 2024).
endometritis (1 paper, 2021). An acute or chronic, usually bacterial infectious process affecting the endometrium. "We found NLRC4−/− and AIM2−/−, NOD1−/−, NOD2−/−, and GBPchr3−/− mice developed severe endometritis at day 56 pi." (PMID 34526512, 2021).
experimental autoimmune encephalomyelitis (1 paper, 2019). An autoimmune demyelinating disease of the central nervous system that is produced experimentally in animals by the injection of homogenized brain or spinal cord in Freund's adjuvant. "Another group studying experimental autoimmune encephalomyelitis (EAE, an animal model disease that resembles MS) showed that peptidoglycan works through receptors NOD1, NOD2, and RIP2 and dendritic cells to worsen the disease." (PMID 30718694, 2019).
female infertility (1 paper, 2024). Diminished or absent ability of a female to achieve conception. "Our findings reveal that the NOD1 rs2075820 AA phenotype and PYDC2 rs293833 (c.242A > G) polymorphism are strongly associated with female infertility." (PMID 40034240, 2024).
gram-negative bacterial infections (1 paper, 2018). Infections caused by bacteria that show up as pink (negative) when treated by the gram-staining method. "The results showed that both Gram-negative bacterial infection and LPS stimulation can induce inflammatory response in teleost fish, NOD1 can also respond to LPS stimulation and Gram-negative bacterial infection." (PMID 30013548, 2018).
Granuloma (1 paper, 2025). A compact, organized collection of mature mononuclear phagocytes, which may be but is not necessarily accompanied by accessory features such as necrosis. "No expression of NOD1 or NOD2 was detected in the focal and diffuse paucibacillary lesions, while a strong expression of NOD2 and occasional NOD1 was observed in the multibacillary granulomas." (PMID 40433460, 2025).
Helicobacter infection (1 paper, 2011). "This cell line is also responsive to Helicobacter infection and expresses NOD1 mRNA." (PMID 22216156, 2011).
hematoma (1 paper, 2020). A hematoma is a collection of blood from a vascular structure into an extravascular space. "However, other hematoma components, such as thrombin and haemoglobin, were not applied in our study, and it will be important to employ them in future studies to gain comprehensive insight into the role of NOD1/RIP2 signalling during ICH." (PMID 33261639, 2020).
hepatitis C (1 paper, 2020). "In the light of increased expression of NOD1 in hepatitis C patients and the involvement of NOD1 through interaction with dsRNA in hepatocytes infected in-vitro or in-vivo with HCV, current observations with PBMCs need to be extended to hepatocytes." (PMID 32012176, 2020).
Hyperglycemia (1 paper, 2019). An increased concentration of glucose in the blood. "We wanted to know whether ablating Nod1 sensing in beta cells may exacerbate hyperglycemia during DIO." (PMID 31201384, 2019). "Thus, the lack of Nod1-mediated gut-islet crosstalk further exacerbates hyperglycemia associated with DIO." (PMID 31201384, 2019).
hyperlipidemia (1 paper, 2014). "Bacterial NOD1 activation is positioned as a component of metabolic endotoxemia that can contribute to hyperlipidemia, systemic inflammation and insulin resistance by acting directly on adipocytes." (PMID 24828250, 2014).
inflammatory bone disease (1 paper, 2025). "We propose that a NOD1 signaling blockade could serve as a therapeutic target for controlling inflammatory bone disease." (PMID 40817410, 2025).
intestinal infections (1 paper, 2014). "More interesting, others have described that intestinal epithelial cells express NOD1 almost exclusively and that gram-negative bacteria are the leading cause of intestinal infections." (PMID 25443778, 2014).
intestinal tumors (1 paper, 2022). "In addition, antibiotic treatment of Nod1 gene-deficient mice significantly inhibits the formation of intestinal tumors, suggesting that gut microbiota play an important role in the development of intestinal tumors, although the specific pathogenic microbial species have not been elucidated." (PMID 35954484, 2022).
ischemia reperfusion injury (1 paper, 2022). Adverse functional, metabolic, or structural changes in ischemic tissues resulting from the restoration of blood flow to the tissue (reperfusion), including swelling; hemorrhage; necrosis; and damage from free radicals. "Nucleotide‐binding oligomerization domain 1 (NOD1) can direct the release of inflammatory factors and influence autophagy and apoptosis in hepatic ischemia‐reperfusion injury (IRI) in mice." (PMID 36092860, 2022).
Japanese encephalitis (1 paper, 2022). A disease due to a virus transmitted by an arthropod). "Thus, NOD1 targeting could be a therapeutic approach to treat Japanese encephalitis." (PMID 35638852, 2022).
lymph node metastasis (1 paper, 2022). "NOD1 was highly expressed in CSCC with lymph-vascular space invasion (LVSI, P < 0.01) and lymph node metastasis (LM, P < 0.01) and related to worse overall survival (OS, P = 0.016)." (PMID 35130902, 2022).
lymphedema (1 paper, 2009). Excess fluid collection in tissues, causing swelling. "BmA also induced significantly higher expression of TLR2, 4, 7, and 9 as well Nod1 and 2 mRNA in patients with lymphedema compared with asymptomatic controls." (PMID 19381284, 2009).
melanoma (1 paper, 2015). A malignant, usually aggressive tumor composed of atypical, neoplastic melanocytes. "Downregulation of other genes associated with this pathway, such as the Nod1 gene that promotes inflammation and Nlrp1 gene that functions to induce apoptosis, would also be expected to contribute to immune escape, enhanced survival, and the overall protumorigenic nature of this melanoma." (PMID 26441959, 2015).
melorheostosis (1 paper, 2025). Melorheostosis is a rare connective tissue disorder characterized by a sclerosing bone dysplasia, usually limited to one side of the body (rarely bilateral), that manifests with pain, stiffness, joint contractures and deformities. "Therefore, NOD1 signaling may represent a novel therapeutic target for treating bone diseases such as osteopetrosis, melorheostosis and heterotopic ossification." (PMID 40817410, 2025).
meningitis (1 paper, 2022). A disorder characterized by acute inflammation of the meninges of the brain and/or spinal cord. "It was observed that the knockout of NOD1 expression in mice resulted in reduced histopathological changes (meningitis and perivascular cuffing) and reduced numbers of activated astrocytes and microglia in brain tissues compared to that in the WT mice." (PMID 35638852, 2022).
nasal polyps (1 paper, 2012). "Relevant to our finding of NRLP3 in the normal mouse bronchiolar epithelium is the recent observation reporting NRLP3 and two other NLRs (NOD1 and NOD2) in upper airway human tissues including normal nasal mucosa, nasal polyps, tonsils, and adenoids." (PMID 22523501, 2012).
Nephropathy (1 paper, 2018). A nonspecific term referring to disease or damage of the kidneys. "We anticipate that the difference in renal pathology between WT and NOD1/2DKO mice in the renal ischemia reperfusion injury model might be due to translocation of bacterial products across the leaky intestinal barrier that activate NOD1/2 resulting in inflammation-associated nephropathy." (PMID 29609537, 2018).
neuropathy (1 paper, 2022). A disorder affecting the nervous system that manifests with pain, tingling, numbness, and/or muscle weakness. "We next investigated whether the inhibition of NOD1, a PGN receptor, could prevent the deleterious effects of PGN on bone marrow neuropathy and on the number and functions of HSPCs." (PMID 35966130, 2022).
oligodendroglioma (1 paper, 2022). A well-differentiated (WHO grade II), diffusely infiltrating neuroglial tumor, typically located in the cerebral hemispheres. "For example, genes located on chromosome 19q (oligodendroglioma, molecular type: IDH-mutated, 1p/1pq-codeleted) and genes located on 7p (NOD1, GSDME, IL6) could be altered by frequent 7p gains in molecular GBM." (PMID 35741587, 2022).
oral diseases (1 paper, 2014). "Given the vital role of NOD1 in innate immune and tissue homeostasis, the inhibitory effect of CSE on NOD1 expression could result in reduced antibacterial peptide production and oral diseases occurrence." (PMID 25503380, 2014).
osteoporosis (1 paper, 2020). A condition of reduced bone mass, with decreased cortical thickness and a decrease in the number and size of the trabeculae of cancellous bone (but normal chemical composition), resulting in increased fracture incidence. "The present study was aimed to investigate the relationship between NOD1/CARD4 and NOD2/CARD15 gene polymorphisms and osteoporosis in the Turkish population." (PMID 32578848, 2020). "In our study examined for the first time, relationship of the NOD1/CARD4 and NOD2/CARD15 polymorphism, which have a role in innate immune response with osteoporosis in Turkish women." (PMID 32578848, 2020). "The first time we thought that the functional polymorphisms in NOD1/CARD4 and NOD2/CARD15 genes might have triggered the development of osteoporosis." (PMID 32578848, 2020). "We thought that the functional polymorphisms in NOD1/CARD4 and NOD2/CARD15 genes might have triggered the development of osteoporosis." (PMID 32578848, 2020). "The NOD1/CARD4 (rs5743336) and NOD2/CARD15 (rs2066847) SNPs were analyzed by PCR restriction fragment length polymorphism (PCR-RFLP) in 94 healthy controls and 164 subjects with osteoporosis." (PMID 32578848, 2020). "Therefore, multicentered studies on different populations and in different gene regions in larger samples are required to establish the correlation between the NOD1/CARD4 and NOD2/CARD15 polymorphisms and osteoporosis." (PMID 32578848, 2020). "The objective of our study was to determine the relationship between NOD1/CARD4 and NOD2/CARD15 SNPs and osteoporosis." (PMID 32578848, 2020). "Our results suggest that the polymorphisms observed in the NOD1/CARD4 and NOD2/CARD15 genes are not genetic susceptibility factors for osteoporosis disease in Turkish women." (PMID 32578848, 2020).
ovarian adenocarcinoma (1 paper, 2025). An adenocarcinoma that arises from the ovary. "The DNA-binding transcription factor activity pathway and the NOD1/2 pathway were identified as negative regulators of tumor cell response to T-cell killing, occurring as late events in breast and ovarian adenocarcinomas." (PMID 39868264, 2025).
ovarian endometriosis (1 paper, 2024). A non-neoplastic disorder characterized by the growth of endometrial tissue in the ovaries. "Our findings suggest that NOD1 rs2075820 AA phenotype and PYDC2 rs293833 (c.242A>G) polymorphism is strongly associated with increased gastrointestinal complaints in ovarian endometriosis patients." (PMID 40034240, 2024). "In this study, we aim to investigate inflammasome regulators PYDC1 and PYDC2 and genetic variations in the NOD1 and NOD2 genes in patients with ovarian endometriosis." (PMID 40034240, 2024).
periodontal diseases (1 paper, 2022). "The result showed a noteworthy increase of NOD1 in the subepithelial connective tissue in the inflamed periodontal tissue, indicating that NOD1 may participate in the progression of periodontal diseases." (PMID 36043447, 2022).
pharyngeal squamous cell carcinoma (1 paper, 2016). A squamous cell carcinoma that arises from the pharynx. "A previous study demonstrated that the pharyngeal squamous cell carcinoma cell lines Detroit-562 cells showed prominent expression of NOD1, and FaDu cells exhibited presence of foremost NOD1, but expressed less NOD2 than did healthy primary human nasal epithelial cells." (PMID 27557518, 2016).
prostate (1 paper, 2022). "NOD1 and NOD2 can be detected in various prostate lesions, including prostatic intraepithelial neoplasia (PIN), phyllodes-like tumors, and adenocarcinoma in transgenic adenocarcinoma of the mouse prostate (TRAMP)." (PMID 35846769, 2022).
pulmonary aspergillosis (1 paper, 2017). "Specifically, in a murine model representing immunocompromised hosts, we assess how NOD1 deficiency influences the host defense during aspergillosis." (PMID 29326692, 2017). "To investigate whether NOD1 plays a role in the susceptibility to aspergillosis, we subjected WT C57Bl6 and Nod1−/− mice to lethal Aspergillus infection." (PMID 29326692, 2017). "It cannot be concluded that the protection against aspergillosis that we observe in Nod1−/− mice is solely due to the increased dectin-1 expression on macrophages." (PMID 29326692, 2017). "Therefore, the current study investigates the role of NOD1 in host defense against aspergillosis." (PMID 29326692, 2017). "However, it is not yet investigated whether NOD1 plays a role in host defense against pulmonary aspergillosis." (PMID 29326692, 2017).
reovirus infection (1 paper, 2018). "In human, NOD1 was significantly induced following stimulation with human cytomegalovirus and in grass carp activation of NOD1 and NOD2 was reported in reovirus infection." (PMID 30119658, 2018).
respiratory syncytial virus infection (1 paper, 2020). "During respiratory syncytial virus infection, NOD2, but not NOD1, can sense single-stranded RNA (ssRNA) from the virus and interacts with mitochondrial antiviral signaling (MAVS)." (PMID 32778560, 2020).
septic peritonitis (1 paper, 2014). Septic peritonitis is an inflammatory condition of the peritoneum that occurs secondary to microbial contamination. "We demonstrate that Nod1 and Nod2 are not involved in the release of chemokines and recruitment of neutrophils to the infectious site during CLP-induced septic peritonitis because these events were similar in wild-type, Nod1-, Nod2-, Nod1/Nod2- and Rip2-deficient mice." (PMID 25084278, 2014).
serous ovarian cancer (1 paper, 2022). "Our studies suggested that high expression of RIPK2 is related to Taxol resistance in serous ovarian cancer, and that RIPK2 induces Taxol resistance through NOD1/RIPK2/NF-κB inflammatory pathway activation and tumor microenvironment changes." (PMID 35477477, 2022).
squamous intraepithelial lesion (1 paper, 2020). "The 47.9% of high-grade squamous intraepithelial lesion (HSIL) (46/96) consisting of CIN II and CIN III and 14.8% of ISCCs (9/61) were positive for NOD1." (PMID 32021648, 2020).
Ureteral obstruction (1 paper, 2018). Obstruction of the flow of urine through the ureter. "To do so, we performed unilateral ureteral obstruction (UUO) in wild type (WT) and NOD1/NOD2 double deficient (DKO) mice and analysed renal damage, fibrosis and inflammation." (PMID 29609537, 2018). "Together these results reveal that there are no or minor changes in the inflammatory response, renal damage and fibrosis following CKD induced by ureteral obstruction in NOD1/2 DKO mice compared with WT mice." (PMID 29609537, 2018). "In the present study we therefore investigated the role of NOD1 and NOD2 in a model of obstructive nephropathy induced by ureteral obstruction." (PMID 29609537, 2018).
vaginal infection (1 paper, 2009). "While Rip2 and Nod1 deficiency increases susceptibility to Listeria monocytogenes and Helicobacter pylori respectively, neither Nod1 nor Rip2 deficiency had any significant effect on Chlamydia muridarum vaginal infection." (PMID 19360122, 2009).
Ventricular arrhythmia (1 paper, 2018). "Therefore, NOD1 emerges as a new potential target in the treatment of cardiac dysfunction and ventricular arrhythmias associated with HF." (PMID 29962957, 2018). "Our data suggest that blocking NOD1 can be a new tool to prevent ventricular arrhythmias and cardiac dysfunction resulting from Ca2+ mishandling in HF." (PMID 29962957, 2018).
Yersinia infection (1 paper, 2009). "We hypothesized that Nod1 and/or Nod2 could be involved in NFκB activation in response to Yersinia infection, as peptidoglycan fragments could have access to the host cell cytosol via the T3SS." (PMID 19997504, 2009).
ZIKV infection (1 paper, 2019). "Activation of NOD1 and NLRC5 was observed following ZIKV infection." (PMID 30781519, 2019).